TNF (tumor necrosis factor)
Diseases named in the same sentence as TNF in open-access papers (continued):
Sharing a sentence is not in itself a finding about the gene and the disease.
Sepsis (continued). "These upstream interventions, such as TNF inhibitors and NF-κB blockers, have shown potential in reducing pathological NO production and mitigating inflammation in autoimmune diseases and sepsis." (PMID 39940974, 2025). "Preclinical studies have shown that agents such as infliximab (anti–TNF-α monoclonal antibody) and tocilizumab (IL-6 receptor antagonist) can reduce tissue injury and improve survival in models of sepsis-induced lung and kidney injury." (PMID 40558557, 2025). "Meanwhile, butyrate, another important SCFAs, attenuated some aspects of sepsis, including serum TNF-α and leaky gut." (PMID 41444762, 2025). "During sepsis, the EG in pulmonary vessels rapidly sheds, and endothelial heparanase is activated by TNF-α, leading to the shedding of heparan sulfate from the EG." (PMID 41280722, 2025). "One study found that IL-6 and TNF-α levels were significantly higher in EOS compared to late-onset sepsis, particularly within the first 48 h of life, reinforcing their value for early diagnosis." (PMID 40806937, 2025). "To characterize the anti-inflammatory effect of DTP against LPS-induced sepsis, we quantified the concentrations of the inflammatory markers TNF-α, IL-6, and IL-1β in mouse serum by ELISA." (PMID 41009021, 2025). "Previous studies have shown that peritoneal acidosis suppressed the immune system by increasing serum IL10 and decreasing serum TNFα levels in rats with lipopolysaccharide (LPS)-induced sepsis." (PMID 40102905, 2025). "In this scenario, proinflammatory cytokines, such as TNF-α, IL-1β, and IL-6, have been confirmed to act in the acute phase of sepsis, mediating the systemic response and progression to multiorgan dysfunction." (PMID 41268545, 2025). "Sepsis also triggers a massive release of pro-inflammatory cytokines, such as interleukin-6 (IL-6), tumor necrosis factor-alpha (TNF-α), and interleukin-1 beta (IL-1β), as well as reactive oxygen species (ROS)." (PMID 40563999, 2025). "In this study, we elucidated the protective role of H2S in sepsis-induced adrenal dysfunction through the inhibition of TNFα-mediated necroptosis." (PMID 40430756, 2025). "The results showed that APACHE II, WBC, PCT, CRP, TNF-α, IL-6, and SOFA scores were the independent risk factors for the 28-day survival of patients with sepsis after high-dose CRRT (all p < 0.05)." (PMID 41393152, 2025). "The inflammatory biomarker TNF-α was markedly increased, peaking one hour after the induction of sepsis." (PMID 39904820, 2025). "In wild-type mice, levels of monocyte chemoattractant protein (MCP)-1, IL-1, IL-6, and TNF-α—elevated after sepsis induction—have been shown to decrease with cetirizine treatment." (PMID 41517447, 2025). "For example, acetylation of histone H3 at the promoter regions of proinflammatory cytokines such as TNF-α and IL-6 has been shown to enhance their transcription and exacerbate liver injury in sepsis models." (PMID 40226624, 2025). "The central role of cytokines like IL-6 and TNF-α in both sepsis and cancer has led to the development of targeted therapies aimed at modulating their activity." (PMID 40563999, 2025). "Systemic inflammation was assessed by measuring TNF-α, IL-1β, IL-6, and MCP-1, which are hallmark inflammatory mediators of sepsis." (PMID 40185975, 2025). "This study demonstrates that TNFα production after LPS challenge is significantly lower in patients with sepsis and bacteremia compared to healthy individuals and those undergoing cardiac surgery." (PMID 40862819, 2025). "MiR-146a has been demonstrated to modulate immune responses during sepsis by targeting pivotal components of the NF-κB and TNF signaling pathways." (PMID 40135054, 2025). "In the ELISA, CBD treatment indicated the downregulation of TNF-α, IL-6, and IL-1β expression levels in the serum samples of the LPS-mediated sepsis mouse models." (PMID 41465451, 2025).
Sepsis (continued). "First, it provides a comprehensive analysis of multiple inflammatory markers, including CRP, IL-1β, IL-6, IL-8, IL-10, PCT, and TNF-α, which offers a detailed understanding of the immunomodulatory effects of ulinastatin in the treatment of sepsis." (PMID 40667510, 2025). "Pro-inflammatory cytokines, including IL-5, IL-6, and TNF-α released in sepsis, cross the blood–brain barrier and act on the hypothalamus and the pituitary to stimulate CRH and ACTH release, respectively." (PMID 39838305, 2025). "CLU levels tend to decrease in patients with severe sepsis and qSOFA ≥2 and correlated inversely with pro‐inflammatory cytokines (IL‐6, TNFα) and inflammatory markers (CRP)." (PMID 40722110, 2025). "The upstream regulator identified in sepsis was TNF, which also suggests that innate immunity is key to the pathophysiology of sepsis." (PMID 40699834, 2025). "In sepsis, inflammatory mediators such as cytokines (TNFα, IL-1β) and NO lead to thr dysregulation of calcium release from the sarcoplasmic reticulum (SR)." (PMID 39941634, 2025). "The key proinflammatory cytokines in sepsis, IL-6 and TNF-α, were both significantly higher in the blood of mice with CLP than in mice with sham operation." (PMID 41157235, 2025). "TNFα and IL1β are pro-inflammatory cytokines involved in several disease and conditions including sepsis and tumor invasion, and both cytokines induce degradation of the EC barrier and expression of adhesion molecules." (PMID 39761260, 2025). "This secondary analysis extends our prior investigation by examining the relationship between previously-described, hyper- and hypo-inflammatory subphenotypes of sepsis and ex vivo TNF production in our cohort." (PMID 40433392, 2025). "In advanced sepsis cardiac dysfunction, inflammatory cytokines (IL-1β, TNF-α) activated by increasing the inducible nitric oxide synthase (iNOS), which further sustains the production of excess NO." (PMID 40356926, 2025). "Our previous studies found that IL-27 levels are elevated in sepsis-associated AHI in humans and in a mouse model of sepsis and that IL-27 plays a role in promoting macrophage M1 polarization and increasing IL-6 and TNF-α levels." (PMID 40046257, 2025). "This highlights the need for additional research, as well as the potential for sepsis-dependent TNFα increases to exhibit tissue or compartment-specific circadian rhythms." (PMID 39968295, 2025). "Systemically, high concentrations of TNF‐α during sepsis contribute to altered chemotaxis, vascular integrity and coagulation, resulting in organ dysfunction." (PMID 40292988, 2025). "Currently, it is widely accepted that severe or fatal sepsis is mediated by inflammatory mediators such as Interleukin (IL)−1, IL-6, and Tumor Necrosis Factor (TNF)-α." (PMID 40054422, 2025). "During the initial phase of SAP or sepsis, a massive release of pro‐inflammatory cytokines (e.g., IL‐6, TNF‐α) establishes a critical immunoregulatory imbalance." (PMID 40464424, 2025). "Even though an extended panel of cytokines has been proposed to participate in sepsis, IL-1β and TNF-α appear to be representative of the two basic mechanisms, namely inhibition of pathogens and tissue damage minimization." (PMID 40142568, 2025). "Tumor necrosis factor-alpha (TNF-α) has been identified as a key cytokine responsible for septic shock in cases of severe sepsis." (PMID 40724987, 2025). "During sepsis, IL-10 is rapidly upregulated in response to pro-inflammatory cytokines such as TNF-α and IL-6." (PMID 41013722, 2025). "Sepsis triggers increased C3, IL-6 and TNF-α in spinal astrocytes, while administration of the α2A-adrenergic receptor (α2-AR) agonist dexmedetomidine blocked inflammatory factor production, neuronal damage, and cardiac dysfunction." (PMID 40692211, 2025).
Sepsis (continued). "PN enhances bacterial clearance in sepsis by modulating adaptive immune responses, including suppression of TNF-α, IL-10, and IL-6 secretion, while concurrently reducing cellular apoptosis and increasing neutrophil counts." (PMID 40725434, 2025). "Heightened inflammation was observed in the TNF-α levels and various organs of the sepsis group; conversely, inflammation was reduced in the group receiving ET treatment." (PMID 40918153, 2025). "A prior study showed significant reductions in plasma IL-6 and TNF-α levels in rats following sepsis induction with Androstenediol administration." (PMID 39955435, 2025). "Inhibiting TLR4 activation reduces JNK protein expression in cardiomyocytes and serum TNF-α levels, alleviating myocardial injury and improving cardiac function during sepsis." (PMID 40640887, 2025). "Our study reveals that sepsis induces a marked elevation of TNFα levels, which are subsequently eliminated by H2S treatment to suppress necroptotic cell death in adrenal tissues." (PMID 40430756, 2025). "Accumulating evidence demonstrates that blockade of inflammatory cascades effectively mitigates sepsis-induced cardiomyocyte pyroptosis, including inhibition of TNF, IL-1, IL-6, IL-7, IL-15, coagulation factors, and complement C5a." (PMID 41256846, 2025). "During the initial inflammatory phase of sepsis, M1 macrophages release cytokines such as tumor necrosis factor-alpha (TNF-α) and interleukin-6 (IL-6), intensifying lung injury." (PMID 39910395, 2025). "In sepsis, cytokine-mediated Nrf2 suppression (e.g., via TNF-α/NF-κB) exacerbates redox-metal-sulfur dysregulation, creating a permissive environment for all three RCD pathways." (PMID 40893878, 2025). "Given that multi-organ dysfunction in sepsis is primarily driven by a hyperinflammatory cytokine storm, we examined serum levels of TNF-α, IL-6, and IL-1β and found that ILA effectively mitigated systemic inflammatory response." (PMID 40761792, 2025). "Due to their central roles in driving harmful inflammation and downstream pathological cascades, TNF-α, IL-6, and IL-1 have been extensively investigated as therapeutic targets in sepsis and other cytokine storm-related conditions, such as severe COVID-19." (PMID 41157235, 2025). "Instead, proinflammatory cytokines, tumor necrosis factor-alpha and interleukin-6, were significantly lower in the Sepsis-plus-hypoxia group compared with the Sepsis group at multiple timepoints." (PMID 41422365, 2025). "The proinflammatory cytokines, including TNF, IL-1, and IL-6, have been identified as potential mediators of the metabolic disturbances in sepsis." (PMID 39838305, 2025). "Proinflammatory cytokines, such as TNF-α and IL-1β, released during sepsis indirectly suppress the activity of the PI3K catalytic subunit p110 via activation of the nuclear factor kappa B (NF-κB) pathway." (PMID 40823184, 2025). "LPS-induced sepsis in C57BL/6 male mice timed to the rest phase has also been shown to align with higher serum TNFα concentrations compared to sepsis initiation during the active phase." (PMID 39968295, 2025). "In some clinical studies, IFN-γ has the potential to improve monocyte dysfunction in sepsis patients by increasing mHLA-DR expression and TNF-α secretion while reducing IL-10 expression, thus reversing immunosuppression." (PMID 40153575, 2025). "Despite advancements in understanding sepsis pathophysiology, translating preclinical findings into effective human therapies remains challenging, as exemplified by the failure of anti-TNF antibodies in clinical trials." (PMID 40303397, 2025). "Nominally pro- (IL-6, MIP-2, TNFα) and anti-inflammatory cytokines (IL-10) form a double-edged sword in sepsis and septic shock and are required to respond to, and eliminate infection, while excessive production causes organ damage." (PMID 41155249, 2025).
Sepsis (continued). "In a systematic review and meta-analysis, it was found that IRAK3 expression and its effect on inflammatory markers (TNF-α and IL-6) varied at different stages of sepsis, affected by changes in experimental procedures." (PMID 40108736, 2025). "TNF-α and IL-6, important pro-inflammatory cytokines, play a key role in the inflammatory cascade of sepsis." (PMID 41393152, 2025). "Since proinflammatory cytokine overproduction is indicative of sepsis, we evaluated the levels of TNF‐α, IFN‐γ, IL‐1α, IL‐1ß, IL‐6, IL‐10, IFN‐ß, IL‐17A, IL‐23, IL‐27, MCP‐1, IL‐12p70, and GM‐CSF in the serum at 16 h after LPS‐induced septic shock." (PMID 39482884, 2025). "Studies have shown that in sepsis models, the activation of NF-κB can increase the production of TNF-α by more than 2-fold, further amplifying the inflammatory response." (PMID 40226624, 2025). "In the sepsis cell model, miR-539-5p has also been found to regulate the levels of TNF-α and IL-1β in cardiomyocytes." (PMID 40955148, 2025). "In sepsis, dysregulated cIAP1/2 activity worsens TNF-α-induced cell death, amplifying myocardial injury." (PMID 39803908, 2025). "Sepsis led to an increase in the expression of IL-6, TNF-α, and a decrease in the expression of occludin." (PMID 40822580, 2025). "The development of septicemia, characterized by persistent fever, hypotension, asthenia, and positive blood and wound cultures, warranted the addition of a TNF inhibitor as an adjunctive therapy." (PMID 41255452, 2025). "Anti-inflammatory agents, such as IL-6 and TNF-α inhibitors, have shown potential in mitigating inflammation in both sepsis and cancer, though their dual roles in protective and pathological processes require careful consideration." (PMID 40563999, 2025). "The repeated failure of cytokine-targeted therapies such as anti-TNF, anti-IL-1, and anti-IL-6 antibodies in sepsis reflects systemic issues in trial design and patient selection rather than the absence of biologic relevance." (PMID 41268545, 2025). "Research indicates that it can reestablish HLA-DR expression in monocytes from sepsis patients, promote TNF-α release, and reverse immunosuppression." (PMID 40153575, 2025). "Age inversely correlated with the percentage of CD8+ T cells positive for IFNγ in sepsis alone (r2 = 0.16, p=0.04) and the percentage of CD8+ T cells positive for TNFα in sepsis alone (r2 = 0.22, p=0.013)." (PMID 39935482, 2025). "Whilst it is generally accepted that circulating cytokines are arrhythmic in healthy adults, in severe infections, including clinical sepsis, some circulating cytokines gain apparent circadian rhythmicity, such as TNFα." (PMID 39968295, 2025). "The innate and adaptive immune systems release inflammatory cytokines early in sepsis to eliminate foreign pathogens, such as IL-6, TNF-α, and IL-1β." (PMID 40718494, 2025). "During sepsis, LPS stimulation elevates the expression and release of proinflammatory cytokines, including IL-6 and TNF-α." (PMID 41256846, 2025). "Recent research has found that CD14+ macrophages and neutrophils are closely associated with the induction and progression of cytokine storms driven by TNF responses in a mouse sepsis model, significantly contributing to lethality." (PMID 40690812, 2025). "Among the perioperative factors that damage the glycocalyx, the most significant are hypervolemia, blood product transfusion, ischemia–reperfusion injury, sepsis, and, in particular, tumor necrosis factor (TNF-α) and lipopolysaccharides (LPS)." (PMID 41149697, 2025). "In sepsis-induced acute lung injury, upregulation of lncRNA H19 inhibited TNF-α, IL-1β, IL-6, IL-10, and BAX to suppress pulmonary apoptosis and inflammation." (PMID 39940682, 2025). "Based on this theory, clinical trials of therapeutic strategies, such as antibody-neutralizing TNF-α or anti-interleukin 1 therapies, were conducted in patients with sepsis." (PMID 40699834, 2025).
Sepsis (continued). "TNF signaling functions in a variety of physiological and disease processes such as immunity, inflammation, sepsis, neurodegenerative diseases, multiple sclerosis, and tumor." (PMID 40575382, 2025). "RA, a chronic autoimmune disease affecting 0.5–1% of the global population, shares unexpected commonalities with sepsis in its inflammatory pathways, particularly the involvement of TNF and other cytokines." (PMID 40303397, 2025). "2DG and oxamate also mitigated sepsis‐induced lung tissue injury as well as systemic proinflammatory responses as represented by decreased plasma levels of cytokine IL‐6 and TNFα." (PMID 39822760, 2025). "In agreement with a previous concept, TNF was upregulated, but the FasL was downregulated in the present study; therefore, the TNF pathway seemed the main trigger for enhancing the proinflammatory response and consequent necroptosis in sepsis." (PMID 40318009, 2025). "In a CLP mouse model of sepsis, the system significantly reduced serum levels of inflammatory cytokines (TNF‐α, IL‐1β, and IL‐6), decreased mortality rates and protected against tissue damage." (PMID 40599085, 2025). "of sepsis induction revealed an exacerbated inflammatory response evidenced by increased tissue levels of proinflammatory cytokines IL‐6, IL‐1β and TNF‐α." (PMID 39444093, 2025). "Restore monocyte HLA-DR expression, enhance TNF-α release, and alleviate immunosuppression in sepsis patients." (PMID 40153575, 2025). "The primary outcomes assessed were levels of inflammatory markers such as IL-1β, IL-6, IL-8, IL-10, CRP, PCT, and TNF-α, providing a comprehensive overview of the effectiveness of the combined therapy on inflammatory responses in sepsis patients." (PMID 40667510, 2025). "Compared with control mice, these mice presented decreased levels of proinflammatory cytokines, such as IL-1β, IL-6, and TNF-α; reduced sepsis-induced organ injury; and improved survival." (PMID 39675717, 2025). "Levels of systemically elevated pro-inflammatory cytokines such as interleukin (IL)−6, IL-1beta and the tumor necrosis factor (TNF) correlated with sepsis severity and organ dysfunction." (PMID 40253667, 2025). "Despite the established link between elevated TNF-α levels and sepsis-related mortality, early trials of TNF-α inhibitors have yielded limited and often statistically insignificant therapeutic benefits." (PMID 40481519, 2025). "Pooled analysis demonstrated that dexmedetomidine decreased the peripheral blood TNF-α level in sepsis patients [SMD = −2.39, 95%CI = (−3.52, −1.27), p < 0.001], with this difference being statistically significant." (PMID 41195185, 2025). "Further, a higher number of IL-10-producing and lower number of TNF-producing CD4+ T cells in PLN substantiate the idea that immunoregulatory surroundings prevail in lymphoid organs after sepsis." (PMID 41142792, 2025). "In sepsis animal models, inflammatory factors such as IL-1β and TNF-α are significantly elevated in both serum and kidney, contributing to the occurrence and progression of AKI." (PMID 40989844, 2025). "The rationale for targeting TNF in sepsis stemmed from its early and prominent role in initiating the inflammatory response." (PMID 40303397, 2025). "Uncontrolled inflammation in sepsis results in an increase in the release of pro-inflammatory cytokines, including tumor necrosis factor alpha (TNF-α), interleukin-1 beta (IL1-β), IL-6, and HMGB-1." (PMID 39838305, 2025). "Randomized controlled clinical trials have also indicated the failure of TNF-α or IL-1 blockade to improve outcomes in sepsis patients." (PMID 39927458, 2025). "Cystatin C levels varied significantly across the different TNF-α (−238, rs361525) genotypes among critically ill patients with sepsis." (PMID 40724987, 2025). "In sepsis models and clinical observations, metformin reduces macrophage TNF-α and IL-6 secretion and alleviates immunosuppression‐associated dysfunction, highlighting its potential in acute inflammation regulation." (PMID 40584964, 2025).